CCR1 (C-C motif chemokine receptor 1)
Diseases named in the same sentence as CCR1 in open-access papers (continued):
Sharing a sentence is not in itself a finding about the gene and the disease.
tumor (237 papers, 2003 to 2026). "Among these, CCR1 is considered the primary receptor mediating the tumor-promoting effects of CCL15, and it has been implicated in cancer metastasis, drug resistance, and progression." (PMID 40740234, 2025). "The recruitment and differentiation of inflammatory monocytes into tumor-associated macrophages, which can facilitate metastasis, are mediated by the CCR1 and CCR2 chemokine axes [3,7,]." (PMID 39566333, 2025). "The combination inhibited CCL15 expression in M2 tumor-associated macrophages and suppressed CCR1 expression on HNSCC cells, suggesting a cooperative immunomodulatory mechanism." (PMID 41156128, 2025). "MC38 and LLC1 Ccl2-deficient tumor cells showed reduced lung metastasis in both Ccr1- and Ccr2-deficient mice when compared to wild-type mice." (PMID 39566333, 2025). "CCR1 antagonists can play a pivotal role in combating cancer cells by suppressing M2 tumor-associated macrophages, which express CCR1." (PMID 37760825, 2023). "On the other hand, as the first-discovered C-C chemokine receptor, CCR1 is overexpressed in several types of cancers and is associated with increased immune-suppressive cell infiltration and tumor metastasis." (PMID 38274805, 2023). "It recruits TAM to the tumor perimeter by binding to CCR1, contributing to the increased susceptibility of tumors to metastasize to the liver." (PMID 36072582, 2022). "Further studies demonstrated that HSPCs primed by tumor derived factors produce CCL3-4, which act via autocrine or paracrine mechanisms on CCR5 and CCR1 to promote the differentiation of tumor associated neutrophils with immunosuppressive properties." (PMID 36561751, 2022). "Mechanistic analysis reveals that Treg depletion causes CAF reprogramming by loss of tumor-restraining αSMA+ fibroblasts and gain of C-C motif chemokine receptor 1 (CCR1) ligand expression, recruiting myeloid cells to restore the immune suppression." (PMID 36230914, 2022). "Tumor-associated macrophages (TAMs) and CC-chemokine receptor 1 (CCR1)+ immature myeloid cells are responsible for the tumor invasion through IL-4-dependent secretion of matrix-degrading enzymes such as MMPs, cathepsins, and heparanase." (PMID 34220337, 2021). "Colorectal cancer models have shown that CCL15 causes tumor-associated neutrophils (TAN) recruitment to the tumor niche via CCR1 on these cells." (PMID 33182504, 2020). "Immunofluorescent staining showed that most CCR1+ cells around lung metastases were tumor-associated neutrophils, although a minor fraction was granulocytic myeloid-derived suppressor cells." (PMID 32332709, 2020). "In this context, a recent report has demonstrated that NF-κB-mediated upregulation CCL2 (an agonist for CCR1/2/3) promotes tumor-associated macrophage infiltration and tumorigenesis in lung cancer." (PMID 33257678, 2020). "In this study it was concluded that CCL15 deletion was associated with diminished CCR1+ cell accumulation in the tumor and limited tumor growth." (PMID 34458892, 2020). "The CC motif chemokine receptor 1 (CCR1) has been implicated in tumor invasion and metastasis in numerous cancers." (PMID 29212252, 2017). "Genetic loss of host CCL3 or its receptor CCR1 reduces the MAM accumulation in the tumor-challenged lung 24 h after tumor injection and decreases number of metastatic foci." (PMID 26275794, 2015). "The aim of this study is to isolate and characterize the tumor-associated myeloid cells that express CCR1 and MMPs." (PMID 25326065, 2014). "Whereas HCC induced by N-nitrosodiethylamine treatment occurred more frequently in both CCL3- and CCR1-deficient mice compared with control mice, tumor burden was dramatically reduced by CCL3 or CCR1 deficiency." (PMID 24646914, 2014). "The specific CCL15–CCR1 pair on tumor cells with high UVRAG expression and stromal cells could recruit tumor-associated neutrophils and CCR1+ myeloid cells, promoting tumor metastasis." (PMID 37173968, 2023).
tumor (continued). "The number of studies related to the role of CCR1 variants in neoplastic diseases is very limited." (PMID 36983384, 2023). "For example, the loss of the tumor suppressor Smad4 in tumor epithelial cells mutated in Apc promotes the invasiveness of intestinal tumors through recruitment of matrix metalloproteinase (MMP)-expressing CCR1+ bone marrow–derived cells to the invasion front." (PMID 36970719, 2022). "For instance, the loss of Smad4 in tumor epithelial cells mutated in Apc enhances expression of the inflammatory chemokine CCL9 to promote malignant progression of the Apc mutant tumors by recruiting MMP-expressing CCR1+ bone marrow–derived cells." (PMID 36970719, 2022). "We then determined whether CCR1 is associated with a more aggressive in vivo progression of tumor growth and its impact on survival." (PMID 32963283, 2020). "However, the mechanism underlying CCR1 upregulation in metastatic tumor cells is poorly characterized." (PMID 29212252, 2017). "Moreover, the inhibition of CCR1 was associated with impairment of osteoclastogenesis and OC-induced tumor cell proliferation in vitro, suggesting that the MIP-1α/CCR1 pathway is an important target in MM bone disease." (PMID 23818912, 2013). "Through mechanistic perturbations of neutrophil-derived CCL3 in mice, we show that it sustains TAN survival in hypoxic tumor regions via CCR1-dependent signaling." (PMID 41650972, 2026). "It not only promotes tumor invasion in an autocrine manner, but it can also specifically recruit monocytes with CCR1+ CD14+." (PMID 40145607, 2025). "Tumor cells can secrete chemokine (C-C motif) ligand 15 (CCL15) to recruit C-C motif chemokine receptor 1 (CCR1)-positive macrophages, thereby facilitating immune evasion and promoting tumor progression." (PMID 40740234, 2025). "This study highlights ZBP1 as crucial for OSCC progression by regulating CCL7 expression in CAFs to activate CCR1 signaling in tumor cells." (PMID 41430036, 2025). "Mechanistically, CCL15 interacts with multiple chemokine receptors, especially CCR1, to recruit macrophages, neutrophils, and lymphocytes, thereby regulating tumor growth 6, 9-11." (PMID 40740234, 2025). "Mmp7 and Ifitm3 are known to promote metastasis in human CRC, and Ccl9 expression by epithelial cells promotes tumor invasion through recruitment of Ccr1+ myeloid cells to the tumor’s invasive front in a mouse model of CRC." (PMID 41384492, 2025). "To reassess the role of Ccr2-mediated monocyte recruitment to lung metastasis, we analyzed the infiltration of Ly6Chi monocytic cells in the lungs of BL6, Ccr1-/- and Ccr2-/- mice, 12- and 24-h post-intravenous tumor cell injection." (PMID 39566333, 2025). "In contrast, tumor-derived NOX4-produced hydrogen peroxide induces M2 polarization through HIF-1α stabilization, creating chemokine gradients (CCL7/IL-8) that recruit CCR1+ immunosuppressive macrophages to support tumor progression." (PMID 40733095, 2025). "Clinical application of CCR1 faces challenges due to its expression on normal immune cells, raising concerns about off-tumor effects." (PMID 40597436, 2025). "CCL14 appears to be the primary recruiter of CCR1+CD14+ monocytes to the tumor mass, with high CCL14 levels correlating with poor prognosis." (PMID 40136652, 2025). "Lastly, we show that Ccl2-knock-down tumor cells in Ccr1-/- mice leads to virtual impairment of lung metastasis." (PMID 39566333, 2025). "Specifically, tumor derived CCL15 expression resulted in the recruitment of CCR1+ cells to the invasive front of colorectal cancer in humans." (PMID 39566333, 2025). "Collectively, these results demonstrate that CCL15 promotes ESCC progression by acting on tumor-intrinsic CCR1." (PMID 40740234, 2025). "Tumors derived from rhCCL15-treated EC109 cells were larger than the control, while CCR1 knockdown led to marked tumor growth inhibition." (PMID 40740234, 2025).
tumor (continued). "The current study extends this paradigm by revealing that in OSCC, ZBP1 indirectly activates the CCR1 pathway in tumor cells by regulating CCL7 expression in CAFs, enhancing their proliferation, migration, and invasion." (PMID 41430036, 2025). "The migration of monocytes derived from BL6, Ccr1-/- and Ccr2-/- mice was dependent on tumor cell-derived Ccl2 in the CM, since migration towards CM from Ccl2KD tumor cells was reduced." (PMID 39566333, 2025). "Here, we discovered that both CCL15 and CCR1 are significantly overexpressed in tumor tissues of patients diagnosed with ESCC." (PMID 40740234, 2025). "The number of macrophages in BL6 mice injected with LLC1.1-Ccl2KD tumor cells was comparable to Ccr1-/- or Ccr2-/- mice injected with LLC1.1-wt, suggesting that both chemokine axes act in a subsequent manner." (PMID 39566333, 2025). "Metastatic foci from LLC1.1-Ccl2KD tumors revealed even less F4/80+ cells in BL6 and Ccr1-/- mice both at the invasive edge and inside the tumor lesions." (PMID 39566333, 2025). "We observed a significant reduction of lung metastasis in Ccr1-/- mice, which was further reduced in mice injected with Ccl2KD tumor cells." (PMID 39566333, 2025). "To test the effect of individual Ccr1- and Ccr2-deficiences, we tested LLC1.1 tumor cells in an experimental lung metastasis model using BL6, Ccr1-/-, and Ccr2-/- mice." (PMID 39566333, 2025). "Correspondingly, a single-cell dot plot analysis indicates that the expression of Ccr1 in tumor cells is significantly reduced in Zbp1−/− mice compared to wild-type (WT) counterparts." (PMID 41430036, 2025). "Another chemokine signalling axis, CCL15 -CCR1 also activates NF-κB pathway by recruiting monocytes, eosinophils and neutrophils to the tumour site ultimately inducing drug resistance." (PMID 40852716, 2025). "Taken together, both Ccr1- and Ccr2-dependent recruitment and stimulation of monocytes/macrophages promote metastasis, which are increased by tumor-derived Ccl2." (PMID 39566333, 2025). "PLAT, a secreted serine protease, has been demonstrated to enhance cancer cell migration and invasion, whilst CCL3, a gene coding for a ligand for CC motif chemokine receptor 1 and 5 (CCR1 and CCR5), has been implicated in promoting tumour growth." (PMID 40998421, 2025). "CCXR721, a selective antagonist for CCR1, blocks the formation of mature osteoclast and experience a profound decrease in the tumour burden." (PMID 40852716, 2025). "Put together, these data suggest that Ly6G+ cells in the bone marrow of TH-302 and αVEGFR-2 treated mice actively proliferate and exit the bone marrow via CCR1 toward the tumor in response to combination TH-302 and VEGFR-2 blockade treatment." (PMID 37988164, 2024). "Meanwhile, neutrophils have been shown to suppress the NK cell infiltration, by downregulating CCR1 and to impair anti-tumor capabilities by cell-to-cell interactions, through the PD-L1/PD-1 axis." (PMID 38915471, 2024). "The mice were fed with HFD and blocked by intraperitoneal injection of CCL9 receptor CCR1 inhibitor J113863, Tumor growth was evaluated for 2 weeks." (PMID 38291436, 2024). "In preclinical mouse models, we also demonstrated that the inhibition of CCR1-mediated myeloid cell accumulation suppressed tumor growth and metastasis." (PMID 39795864, 2024). "On day 35 post-inoculation, the tumor size in Ccr1−/−Cxcr2−/− > WT mice was 794 ± 104 mm3, whereas those in WT > WT, Ccr1−/−>WT and Cxcr2−/− > WT mice were 2198 ± 525 mm3, 1243 ± 352 mm3 and 1188 ± 246 mm3 (P < 0.05, <0.05 and <0.05)." (PMID 38750114, 2024). "As a clinically applicable CCR1 inhibitor, we previously established a novel neutralizing anti-CCR1 mAb, KM5908, which was proven to suppress CCR1+ myeloid cell accumulation and tumor progression in preclinical mouse models." (PMID 38750114, 2024). "In transgenic Apc+/∆716/Smad4+/- compound knockout mice that develop CRC, CCL9 is secreted from cancer cells, which recruits CCR1+ myeloid cells to promote tumor invasion." (PMID 38750114, 2024).
tumor (continued). "Together, these data indicate that the CCL9/CCR1 axis probably plays a role in the influx of G-MDSCs into the tumor after treatment with TH-302 and VEGFR-2 blockade." (PMID 37988164, 2024). "Mice reconstituted with Ccr1−/−Cxcr2−/− BM exhibited the strongest suppression of tumor growth and liver metastasis compared with other three groups." (PMID 38750114, 2024). "In livers of nude mice, SMAD4-deficient human CRC cells (AA/C1, HT29, Colo205, LoVo, DLD-1, and HCT116) displayed CCL15 upregulation and increase in CCR1(+) cells recruitment that promoted tumor invasion." (PMID 37185750, 2023). "C3AR1 expression was positively correlated with chemokines and their receptors in the tumor microenvironment, such as CCR1(R = 0.83), IL10RA (R = 0.92), and INFG (R = 0.74)." (PMID 37005667, 2023). "In the APC/SMAD4 mutant mouse model of CRC, the expression of CCL9 was found to be upregulated in the tumor epithelium and knockout of CCR1 prevented immature myeloid cell (also known as myeloid derived suppressor cells or MDSCs) accumulation at the tumor." (PMID 36982211, 2023). "The CCL3-CCR5/CCR1 signaling pathway plays an important role in the process by which TAMs influence tumor development." (PMID 36173487, 2023). "ILC1 also upregulates CXCR6, CCR5, CXCR3, and CCR1 which can recruit RORγt+ ILC3s to the tumor leading to the inhibition of tumor growth." (PMID 38567059, 2023). "Differential expression analysis in the MACS-sorted cells revealed a significantly higher expression of CCR1 in the tumor cells compared to the ASCs." (PMID 37444610, 2023). "Double immunofluorescence microscopy showed that tumor-infiltrating CD11c+ cells were positive for CCR1 and CCR2 (receptors of CCL7) in the control group." (PMID 37046033, 2023). "Lungtumor-outgoing ligand CCL connected to the tumor and AN as incoming signals via the receptors CCR1 and ACKR2/4, respectively." (PMID 37106167, 2023). "Blockade of CCR1 using pharmacological inhibitors is able to strongly abrogate TAM induced GL261 tumor invasion in in-vitro assays." (PMID 36982211, 2023). "While splenic CD11b+ from the different groups were equally suppressive, CD11b+ cells from the tumor of mice treated with CCR1 and CCR5 shRNAs showed a reduced suppressive activity." (PMID 35064009, 2022). "Briefly, BALB/c or NSG mice were challenged with the 4T1 tumor orthotopically and treated intravenously with 4PD loaded with scrambled or CCR1 and CCR5 shRNAs 3, 5, 7, 10 and 12 days after challenge." (PMID 35064009, 2022). "Phenotypic and functional analysis of the tumor microenvironment pointed us to the presence of classical neutrophils as the main mechanism for the antitumor activity induced by CCR1 and CCR5 silencing." (PMID 35064009, 2022). "Some new interactions have been observed between MDSCs and mature osteoclasts or progenitor osteoclasts in tumor tissues, suggesting that MDSCs are recruited to tumor tissues (CCL3L1_CCR1, CXCL2_DPP4 and CCL3L1_DPP4)." (PMID 36466840, 2022). "Previous data indicate that CCL3/CCR1 signaling regulates tumor cell macrophage interactions that, once established, deliver a survival signal to the tumor cells through engagement of αV-integrin expressed on MAMs and VCAM1 on the tumor cell." (PMID 36077870, 2022). "CCR1 inhibition, on the other hand, suppresses the accumulation of MR+Ly6C- pro-tumour IM at later stages, accompanied by the expansion of the AM compartment and infiltration of NK cells, resulting in reduced metastatic burden." (PMID 36241867, 2022). "In our study, CCR1 blockade with the antagonist J-113863 led to a reduced metastatic tumour burden due to fewer large colonies." (PMID 36241867, 2022). "Additional injection of ECI301 (an active variant of CC chemokine ligand 3) after RFA significantly augmented RFA-induced anti-tumor immune responses and increased CCR1-expressing CD11c+ cells in peripheral blood and tumors." (PMID 36505437, 2022).
tumor (continued). "In GeneSubgroup3, patients were short of various types of chemokines (such as CCR1) and tumor necrosis factors as well as their superfamily members, which were crucial for attracting immune cells and inducing tumor apoptosis." (PMID 35493068, 2022). "In our analysis, NEIL3 expression was positively correlated with pro-tumour chemokine receptors, such as CCR1, to some extent, but negatively correlated with anti-tumour receptors, such as CX3CR1, across cancers." (PMID 36612106, 2022). "Deficiency of CCR1 impaired the accumulation of CD11C+, CD4+ and CD8+ cells in tumors, indicating that ECI301 augmented tumor-specific immune responses through CCR1-mediated DC accumulation in tumor." (PMID 36505437, 2022). "The silencing of CCR5 and CCR1 expression on myeloid cells, including the myeloid precursors, was sufficient to inhibit tumor progression across multiple mouse models." (PMID 36561751, 2022). "CCL3/CCR1 is another pathway that is related to immune cells migration, inflammatory activation, immune responses, and tumor growth." (PMID 36499169, 2022). "Previous studies indicated that this association was through the tumor cell surface expression of VCAM1 and alphaV integrin on the MAMs, whose activity was stimulated by CCR1 signaling." (PMID 36077870, 2022). "When it comes to the CCR1, tumour cells secrete chemokines, which act on stromal cells through CCR1 to induce chemotaxis, and cooperate with stromal cells, promote the invasion process and transfer to the blood circulation or lymphatic system." (PMID 35735060, 2022). "Previous reports have shown that CCR1 expression was the lowest in M1 macrophages but the highest in tumor-educated macrophages." (PMID 36532057, 2022). "This signaling includes expression of CCR1 required for MAM adhesion to extravasated tumor cells that in turn delivers a survival signal to these cells." (PMID 36077870, 2022). "To this aim, we injected 4PD loaded with an equimolar mixture of shRNAs against CCR1, 2, 5, and 7 intravenously to 4T1 tumor bearing mice." (PMID 35064009, 2022). "qRT-PCR analysis of CD11b+cells from the tumor or the spleen of 4T1 bearing mice indicates that CCR1, 5 and 7 are significantly upregulated at the tumor whereas CCR2 is highly expressed on myeloid cells from both tissues." (PMID 35064009, 2022). "CCR1 blockade, in contrast, suppressed late phase pro-tumour MR+Ly6C- monocyte/macrophage infiltration accompanied by expansion of the alveolar macrophage compartment and accumulation of NK cells, leading to reduced metastatic burden." (PMID 36241867, 2022). "have suggested that the deletion of Smad4 in CRC promotes the expression of CCL15 and recruits more CCR1+ TANs and matrix metalloproteinase-9 to the metastatic site to form the premetastatic niche of disseminated tumor cells." (PMID 35912260, 2022). "We purified CD11b+ myeloid cells from the spleen and the tumor of mice treated with CCR1 and CCR5 shRNAs or with scrambled shRNAs and tested their suppressive activity against HA specific, CD8+ T cells stimulated with the relevant peptide." (PMID 35064009, 2022). "Within the glioblastoma TME, CCL5 produced by GAMs, mesenchymal stem cells (MSCs) and tumour cells signals through CCR1, CCR5 and CD44." (PMID 33803414, 2021). "Mechanistically, they secrete CC-chemokine ligand 6 (CCL6) to attract tumor cells to the bone metastatic niche through CC-chemokine receptor 1 (CCR1)." (PMID 34745140, 2021). "C-C motif chemokine ligand (CCL) 5 is expressed in various types of stromal cells and associated with tumor progression, interacting with C-C chemokine receptor (CCR) 1, 3 and 5 expressed in tumor cells." (PMID 33671956, 2021). "Most of the therapeutic benefits of targeting CCR1 stem from reduced MDSC infiltration that culminates in the restraint of tumor growth and metastasis." (PMID 34575965, 2021).